PFKFB3 (6-phosphofructo-2-kinase/fructose-2,6-biphosphatase 3)
Diseases named in the same sentence as PFKFB3 in open-access papers (continued):
Sharing a sentence is not in itself a finding about the gene and the disease.
cancer (continued). "PFKFB3 also induces non-stem cell differentiation to cancer stem cells, depending on the glycolysis and supporting the direct role in rapid cell proliferation and metastasis of cancer cells." (PMID 36077431, 2022). "Some studies have found that PFKFB3 plays a key role in the repair of DNA damage by homologous recombination, leading to the development of the small-molecule PFKFB3 inhibitor KAN0438757, suggesting that PFKFB3 may play a key role in the initiation and development of malignant tumors." (PMID 36230492, 2022). "Reports on the importance of PFKFB3 and PFKFB4 in cancer development and progression strongly suggest that these isozymes may represent promising targets for new potent personalized therapies in cancer treatment." (PMID 33671514, 2021). "Inhibition of PFKFB3 leads to the defective recruitment of FANCM, BLM, FANCD2, and FANCI repair proteins, which are essential for successful ICL repair during replication, recovery of DNA synthesis upon fork stalling, and cancer cell survival upon treatment with ICL-inducing agents." (PMID 34298817, 2021). "Recent discoveries related to PFK-2 isozymes, especially PFKFB3 and PFKFB4, in cancer progression and development, have identified their inhibitors as potent therapeutic agents that could play an important role in future cancer treatment." (PMID 33671514, 2021). "The results obtained by the xCELLigence assay suggested that PFKFB3 inhibition by KAN0438757 could affect cell-substrate attachment, thus we decided to assess the effects of KAN0438757 on cell motility and cancer cell invasiveness in vitro." (PMID 33671096, 2021). "Furthermore, we highlight crucial studies on targeting PFKFB3 and PFKFB4 for future cancer therapy." (PMID 33671514, 2021). "Next, to evaluate whether modifications in PFKFB3 protein expression were due to possible changes in its transcription, we incubated HCT-116 and HT-29 cancer cells for 4, 6, 12, 24 and 48 h with 10 and 25 μM KAN0438757 and subsequently performed RT-PCR analyses for PFKFB3 mRNA expression." (PMID 33671096, 2021). "Obviously, more data are needed to prove the tolerability of this treatment, but it seems that specific inhibition of PFKFB3 does not substantially interfere with physiological processes at the system level; therefore, it represents a promising target for cancer treatment." (PMID 33922320, 2021). "Firstly, inhibition of glycolysis upstream of PFKFB3 by 2-DG did not result in a cancer-specific synthetic lethality with carboplatin, in line with the previously reported non-glycolytic role of PFKFB3 in promoting cell proliferation from its nuclear localization." (PMID 34298817, 2021). "Taken together, inhibition of PFKFB3 enzymatic activity resulted in a non-reversible cancer-specific synergy with platinum drugs in both treatment-sensitive and resistant cell models in contrast to general inhibition of glycolysis which shows toxicity towards non-transformed cells." (PMID 34298817, 2021). "Collectively, PFKFB3i and platinum treatments do not induce differential responses in glycolysis across cancer transformation, thus the cancer-specific synergies between PFKFB3 inhibition and platinum drugs in viability assays are not due to differences in metabolic responses measured." (PMID 34298817, 2021). "Owing to the aberrant expression of PFKFB3 and PKM2 in cancer cells compared with their corresponding “normal” cell counterparts, targeting these glycolytic enzymes might provide a means to target Ca2+ pumps specifically in cancer cells." (PMID 32825277, 2020).
cancer (continued). "Without doubt, it is worth noting that PFKFB4 and PFKFB3 isoenzymes are not only involved in glucose metabolism but may also regulate other processes crucial for carcinogenesis, having a multi-level anti-cancer effect." (PMID 31754349, 2019). "In summary, we identify a key role for PFKFB3 enzymatic activity in HR repair and present KAN0438757, a selective PFKFB3 inhibitor that could potentially be used as a strategy for the treatment of cancer." (PMID 30250201, 2018). "A pervious study demonstrated the higher expression of PFKFB3 in cancer stem cells (CSCs) rather than the induced pluripotent stem cells (iPS), which might be able to be used to distinguish these two kind of stem cells." (PMID 28061878, 2017). "Importantly, 5MPN does not inhibit recombinant PFK-1 or PFKFB3 which share the substrate-binding domain and are also expressed in multiple cancer cell lines yet still reduces the glycolysis and intracellular F2,6BP of cancer cells." (PMID 26221874, 2015). "However, other types of cancers, such as breast, colon, lung, pancreatic, prostatic and ovarian, express high levels of PFKFB3 protein relative to the non-malignant adjacent tissue." (PMID 24280138, 2013). "Since the activity of these compounds towards other PFKFB proteins has not yet been established, their antiproliferative effect on cancer cells may not be solely ascribed to the inhibition of PFKFB3." (PMID 24280138, 2013). "We next analyzed whether PFKFB3 is pronominally expressed in TAMs, but not in cancer cells." (PMID 41516095, 2025). "In this regard, studying the modulatory effects of miRNAs and lncRNAs on those glycolytic proteins linked with cancer progression, e.g., HK1, GAPDH, PKM2, GLUT1, GLUT3, HIF-1α, CAV1, Ras, HK2, LDHA, PGI/AMF, and PFKFB3, might be very favorable for the design of novel treatments for PC." (PMID 36332600, 2023). "Although PFKFB3 is a bifunctional enzyme in glycolysis and catalyzes the synthesis and degradation of the allosteric modulator Fructose 2,6-bisphosphate, PFKFB3 has the capacity to drive cancer cell proliferation from its nuclear localization without modulation of glucose metabolism." (PMID 34298817, 2021). "When the concentrations of CBPt or Cis required to inhibit cancer cell growth by 50% (IC50) were compared with and without PFKFB3 KD, silencing PFKFB3 in chemoresistant HEC-1B and ARK-2 cell lines significantly reduced the average CBPt and Cis IC50s." (PMID 33420377, 2021). "The different expression levels of PFKFB3 and PFK-1 among CSC, iPS cells and non-stem cancer cells suggest improved prospects for the more precise detection of CSCs and for clinical applications of stem cell-based therapies." (PMID 29263928, 2017). "Of significance, PFKFB3 inhibition at ZT7, but not at ZT19, decreased cancer cell production of lactate." (PMID 27079271, 2016). "Expression of PFKFB3 is not typical of liver tissue; however, this isoform is also known as inducible PFKFB, as it has been observed to be expressed in response to hypoxic conditions of cancer cells by hypoxia inducible factor 1-alpha (HIF1α)." (PMID 33083755, 2020). "More precisely, the level of PFKFB3 but not that of other PFKFBs, as a target of HIF-1α that displays the highest phosphofructo-2-kinase activity, is significantly elevated in aggressive cancers, such as PDAC, colon cancer, and breast carcinoma." (PMID 33256814, 2020). "Consistently, PFKFB3 inhibition at ZT7, but not at ZT19, reduced cancer cell proliferation." (PMID 27079271, 2016). "In summary, we have demonstrated that two glycolysis-promoting, R-point-specific enzymes, PFKFB3 and PFK1, may serve as tool enabling discrimination of CSCs from non-stem cancer cells as well as iPS cells." (PMID 26337471, 2015). "Furthermore, we speculate that the reason for AZ PFKFB 67 does not induce cell death by itself, even in MCL-1-addicted cancer cells, is that the remaining MCL-1-protein levels following AZ PFKFB3 treatment may be sufficient to sustain cell survival." (PMID 37684238, 2023).
cancer (continued). "It has been suggested that inhibiting the HIF-1α/PFKFB3/PFK-1 axis with metformin could suppress glycolysis and impair cancer growth in hepatocellular carcinoma, but whether similar effects can be achieved in other cancers is not yet clear." (PMID 33256814, 2020).
infection (24 papers, 2014 to 2026). The state of being infected such as from the introduction of a foreign agent such as serum, vaccine, antigenic substance or organism. "Of note, at 6 h post-infection, the induction of the gene encoding 6-phosphofructo-2-kinase/fructose-2,6-biphosphatase 3 (PFKFB3) a member of the of phosphofructokinase (PFK)-2 family, was more prominent in CDC1551-infected BMDMs." (PMID 32903583, 2020). "The majority of the glycolysis genes showed a significant decline in transcription after infection, but at the same time, the expression of genes that regulate key enzymes like Pfkfb3 and Pdk1 in glycolysis were upregulated." (PMID 38992966, 2025). "To elucidate the pathogenesis of PFKFB3 in FK, we explored its expression in animal and cellular infection models." (PMID 41425966, 2025). "Western blot backed up immunofluorescence discoveries, pointing to that fungi-infection induced vital phosphorylation level of NF-κB p65, AKT, and PI3K in BMDM, these targets were notably enhanced following PFKFB3 deficiencies." (PMID 41425966, 2025). "An additional four genes were upregulated in ΔprgH STm infection and were involved in the regulation of glycolysis (PFKFB3) and cytokine signaling (SOCS3), and intracellular signaling (RASD1, TRAF3IP2)." (PMID 37854334, 2023). "Third, we inhibited glycolysis and cellular pyruvate and lactate production via Pfkfb3 knockdown in RAW264.7 cells before STM infection, and found that creB transcription of the intracellular STM was significantly decreased upon Pfkfb3 knockdown." (PMID 33563986, 2021). "Two major metabolic genes involved in M1 polarization were significantly upregulated 5 and 24 h post-infection, the PFKFB3 gene, which stimulates glycolysis, and the ACOD1 gene, involved in itaconate production." (PMID 34399615, 2021). "In line with its enhanced transcriptional activity, the expression of the PFKFB3 protein was also increased early after infection." (PMID 34044589, 2021). "Knockdown of PFKFB3 by infection HUVEC with adenoviral PFKFB3 resulting in dramatically inhibition expression of angiogenetic genes, as well as tubulogenesis and extracellular matrix related genes." (PMID 33028909, 2020). "Gene expression analysis using a more detailed time course of infection demonstrated that induction of glycolytic genes such as GLUT1, hexokinase 2 (HK2), and PFKFB3 initiated early after the challenge, and was sustained throughout infection." (PMID 32385235, 2020). "The expression levels of GK and PFKFB3 in the S. aureus group were higher than those of the mock infection group (p < 0.001, respectively)." (PMID 31093495, 2019). "Furthermore, treatment with LW6 significantly inhibited PFKFB3-driven glycolysis induced by infection with N. caninum and the replication of N. caninum tachyzoites in caprine EECs and mouse uterine tissues." (PMID 40307939, 2025). "Additionally, it has been reported that PFKFB3-driven host cell glycolysis affects infection and intracellular survival of several pathogens, such as respiratory syncytial virus and Staphylococcus aureus." (PMID 40307939, 2025). "Furthermore, PFKFB3-driven glycolysis has been reported to be critical in the pathophysiological processes of several diseases by altering the expression or phosphorylation of PFKFB3 (e.g. Ser461), particularly in the context of infections of intracellular pathogens." (PMID 40307939, 2025). "Interestingly, under normoxic condition, the loss of Hnrnpk by Ad-Cre infection resulted in the increased expression of Pfkfb3 but not Ldha." (PMID 36127325, 2022). "It is also apparent from our results that in addition to the expression of the PFKFB3 gene, infection of hSMs with the UT127 strain also induced higher levels of HIF1A, HK1, HK2, PDP1, and PDP2 genes compared with the infection with UT205." (PMID 35163725, 2022). "The three ISGs with the most significant inhibitory effect, PFKFB3, BTN3A3, and CCDC92, decreased EBOV∆VP30 titers by nearly 1000-fold on day 6 post infection." (PMID 32528005, 2020).
infection (continued). "Active and VBNC infection of M0-BMDM induced a strong expression of these glycolytic genes at 24 h post-infection, and infection with HK + 1 induced the expression of Hk2, Pfkfb3, and Acod1." (PMID 39714095, 2025). "However, due to the presence of extensive damage to epithelial cells in the DSS model, we do not rule out the possibility that PFKFB3 in IECs may play some role in inflammatory response and defenses against intestinal pathogen infection." (PMID 41378888, 2026).
inflammation (5 papers, 2021 to 2026). Aberrant reaction of the microcirculation characterized by movement of fluid and leukocytes from the blood into extravascular tissues. "Zou investigated the role of PFKFB3 in regulating FLS-mediated synovial inflammation and bone erosion and discovered that PFKFB3 expression was increased in FLS from RA compared with that from OA." (PMID 38482018, 2024). "Our study first elucidates the relationship of PFKFB3 in macrophages with intestinal inflammation and gut microbiota in UC, which may provide a new strategy for the treatment." (PMID 41378888, 2026). "Furthermore, PFKFB3 knockdown significantly inhibited TNF-α-induced endothelial inflammation." (PMID 34021541, 2021).
retinopathy (3 papers, 2023 to 2024). "Interestingly, in animal models of macular degeneration and retinopathy, which both are caused by blood vessel hyperproliferation, targeting PFKFB3 can also enhance the effect of VEGF signaling blocking on angiogenesis." (PMID 39318551, 2024). "Furthermore, inhibition of glycolysis in Mac-specific Pfkfb3–/– mice reduced angiogenesis during oxygen-induced retinopathy and CNV." (PMID 36821388, 2023).
adenocarcinoma (2 papers, 2011 to 2022). A common cancer characterized by the presence of malignant glandular cells. "The poor clinical stage was relevant to PFKFB3 overexpression (adenocarcinoma: P = 0.002, others: P = 0.047)." (PMID 35094634, 2022). "We examined the effect of the PFKFB3 inhibitors, N4A and YN1, on the proliferation rate of human adenocarcinoma cells." (PMID 21957443, 2011).
cardiovascular disease (2 papers, 2021 to 2023). "6-phosphofructo-2-kinase/fructose-2,6-biphosphatase 3 (PFKFB3), an enzyme that regulates glucose metabolism, also plays an important role in various fibrotic and cardiovascular diseases." (PMID 37509108, 2023). "Previous studies have shown that PFKFB3 has detrimental effects on a variety of cardiovascular diseases, such as pulmonary hypertension and atherosclerosis." (PMID 37509108, 2023).
neurodegenerative disease (2 papers, 2024 to 2025). A disorder of the central nervous system characterized by gradual and progressive loss of neural tissue and neurologic function. "PFKFB3, a regulator of glycolytic metabolism, is implicated in neurodegenerative diseases like Alzheimer’s, where it affects amyloid-beta accumulation and neuronal dysfunction." (PMID 40643497, 2025). "AZ-67 was shown to significantly inhibit angiogenesis in vivo at low doses and specifically bind to PFKFB3, while AZ-67 also promoted normalization of the PFKFB3 content in neurons and also had a potential therapeutic effect on neurodegenerative diseases." (PMID 38341583, 2024).
bacterial infection (1 paper, 2025). "In this article, we shortlisted activated target genes in monocytes during acute bacterial infection, including VNN1, NLRC4, CYP1B1, PFKFB3, LILRA5, NFKBIA or NFKBIZ." (PMID 40581066, 2025). "Other monocyte informative genes were also activated in patients with bacterial infection including NLRC4, CYP1B1, PFKFB3, LILRA5, NFKBIA, and NFKBIZ." (PMID 40581066, 2025).
CNS tumors (1 paper, 2021). "As PFKFB3 can be reciprocally induced by activated mTORC1, PFKFB3 appears to be involved in a vicious cycle of continuous overexpression and oncogenicity in various CNS tumors." (PMID 34831136, 2021). "Although the data linking PFKFB3 tumorigenesis to CNS tumors are sparse, there are extensive data documenting the oncogenicity of many PFKFB3 inducers to poor prognosis in CNS neoplastic disease." (PMID 34831136, 2021). "Further investigation on possible PFKFB3 roles in CNS tumor immunotherapeutic resistance can provide an additional treatment modality to the neuro-oncology armamentarium." (PMID 34831136, 2021). "Despite the genomic and oncogenic signatures of CNS tumors being heterogenous, targeting common and critical metabolic pathways via PFKFB3 could synergize targeted treatments." (PMID 34831136, 2021). "Although there is a paucity of PFKFB3-mediated chemotherapeutic and radioresistance data in CNS tumors, further characterization of such effects might prove fruitful." (PMID 34831136, 2021). "However, targeted PFKFB3 inhibition may provide a therapeutic option for CNS tumor patients." (PMID 34831136, 2021). "However, not all PFKFB3 inhibitors have robust enough data for in-human use, and, as such, we will discuss only those with the most promising therapeutic potential for CNS tumors." (PMID 34831136, 2021). "However, the direct link between TSC LOH and PFKFB3 has not yet been studied in CNS tumors." (PMID 34831136, 2021).
heart disease (1 paper, 2021). "Our study demonstrates a pathological role for amylin in the activation of HIF1α and PFKFB3 signaling in NHPs with HF, establishing amylin as a promising target for heart disease patients." (PMID 33580152, 2021).
hematologic disease (1 paper, 2017). "PFKFB3 protein expression is found significantly higher in rapid proliferation cells, such as in solid tumors and hematologic malignancies." (PMID 28977989, 2017).
infectious disease (1 paper, 2025). A disorder directly resulting from the presence and activity of a microbial, viral, or parasitic agent in humans. "PFKFB3 is an important regulatory enzyme of glycolysis flux in several infectious diseases." (PMID 40307939, 2025).
PFKFB3 also shares sentences with these, for which no sentence is quoted: metabolic disorders (6 papers); cardiac hypertrophy (4); benign neoplasm (3); chronic kidney disease (2); multiple myeloma (2); skin carcinoma (2); triple-negative breast carcinoma (2); acute leukemia (1); asthma (1); Batten disease (1); brain cancer (1); breast invasive carcinoma (1); calcification (1); cholangiocarcinoma (1); colorectal adenoma (1); corneal ulcer (1); diabetic cardiomyopathy (1); diabetic retinopathy (1); diffuse large B-cell lymphoma (1); Disc Degeneration (1); endocervical adenocarcinoma (1); gallbladder cancer (1); gastric adenocarcinoma (1); glucocorticoid deficiency (1); glycolysis (1); head and neck cancer (1); Hyperinsulinemia (1); hypothyroidism (1); intestinal inflammation (1); invasive ductal carcinoma (1).
A further 39 diseases each share a sentence with PFKFB3 in 1 paper.